TIMP3 (TIMP metallopeptidase inhibitor 3)
Diseases named in the same sentence as TIMP3 in open-access papers (continued):
Sharing a sentence is not in itself a finding about the gene and the disease.
Hyperglycemia (8 papers, 2011 to 2025). An increased concentration of glucose in the blood. "Animals double-heterozygous for the insulin receptor and Timp3 developed spontaneous mild hyperglycemia and hyperinsulinemia at three months, and overt glucose intolerance and hyperinsulinemia at six months." (PMID 21980496, 2011). "The results showed that 12 weeks after STZ administration, 87% (14/16) of wt mice exhibited hyperglycemia compared to 45% (9/20) of MacT3 mice, indicating that TIMP3 overexpression in cells of the myeloid lineage significantly reduced the susceptibility to type 1 diabetes (p < 0.01)." (PMID 33634991, 2021). "It was mentioned earlier that TIMP3 decrease is responsible for enhanced muscle, vascular and adipose tissue inflammation in diabetic Insr+/− mice compared to non-diabetic Insr+/− mice and double heterozygote Insr+/−/TIMP3+/− mice were insulin resistant and exhibit overt hyperglycemia." (PMID 37445827, 2023). "Moreover, hyperglycemia increases matrix metalloproteinases and ADAM activities, which may be linked to unbalanced expression of TIMP-3." (PMID 27579151, 2016). "It had been shown that TIMP3 expression was decreased in the kidney of STZ treated-mice, a well-known model for hyperglycemia and glucotoxicity, reproducing T1D28." (PMID 35773317, 2022). "Here we report that TIMP3 expression was reduced in the kidney of STZ treated-mice, a well-established model of hyperglycemia and glucotoxicity." (PMID 23401241, 2013). "To test the role of TIMP3 and ADAM17 in DKD we treated C57Bl6 WT mice with streptozocin (STZ) to induce hyperglycaemia." (PMID 23401241, 2013).
prostate tumor (8 papers, 2005 to 2025). "A previous study demonstrated that TIMP-3 deficient mice promote prostate tumor growth, cell proliferation index, micro-vessel density, invasive capacity and the expression of MMP-9." (PMID 33730072, 2021). "For example, miR-17-3p was found to increase tumor cell proliferation, colony formation, cell survival and invasion by targeting TIMP3 in prostate tumor." (PMID 28178677, 2017). "Both miR-17-5p and miR-17-3p have been implicated in co-ordinately targeting the TIMP metallopeptidase inhibitor 3 (TIMP3) gene and induce growth and invasion of prostate tumour." (PMID 25993098, 2015). "The promoter region of TIMP-3 was found to be methylated in 97% of prostate tumors and two studies found TIMP-3 promoter methylation in 37% and 41% of urine sediments from PCa patients." (PMID 22547956, 2011). "Our study showed that ability of mature miR-17-5p and the passenger strand miR-17-3p to synergistically enhance prostate tumor growth and invasion by repressing the same target TIMP3 may be a mode of miRNA-mediated gene regulation." (PMID 23990326, 2013). "Of the genes reported to be frequently differentially methylated between African American and European American prostate tumours (e.g., RARB, TIMP3), none were significantly differentially methylated in our cohort." (PMID 41057544, 2025).
Alzheimer disease (7 papers, 2017 to 2023). A progressive, neurodegenerative disease characterized by loss of function and death of nerve cells in several areas of the brain leading to loss of cognitive function such as memory and language. "TIMP-3, the levels of which are elevated in Alzheimer’s Disease, inhibits the surface expression of ApoER2 and its α-secretase induced cleavage." (PMID 30304853, 2018). "The diverse roles of Timp3 in inflammation, angiogenesis, and extracellular matrix turnover/degradation, have made it a closely looked at molecule for complex degenerative diseases including Alzheimer’s disease and AMD." (PMID 36969592, 2023). "Recently, an increase in TIMP3 was reported in Alzheimer’s disease (AD) brains, while in the SOD1G93A mouse model of ALS, high levels of TIMP-3 were observed only in the early phase of the disease, reducing at later stages proportionally with the number of live motor neurons in the spinal cord." (PMID 36768220, 2023). "However, studies on the amount of TIMP-3 in bodily fluids of Alzheimer’s disease (AD) patients have not been conducted." (PMID 35629249, 2022).
cholangiocarcinoma (7 papers, 2010 to 2022). A carcinoma that arises from the intrahepatic biliary tree (intrahepatic cholangiocarcinoma) or from the junction, or adjacent to the junction, of the right and left hepatic ducts (hilar cholangiocarcinoma). "Inhibition of miRNA-21 results in the up-regulation of PDCD4 and tissue inhibitor of metalloproteinase 3 (TIMP3), a protein which inhibits metalloproteinases (MMPs) and invasion in cholangiocarcinomas." (PMID 35847932, 2022). "Timp3 is a matrix metalloproteinase with proapoptotic activity whose expression is significantly lower in human cholangiocarcinomas." (PMID 20959002, 2010). "It has been suggested that Timp3 may serve as a tumor suppressor gene in cholangiocarcinoma." (PMID 20959002, 2010). "It plays important roles in the progress of cholangiocarcinoma through targeting PTEN/AKT pathway, TIMP3 (tissue inhibitor of metalloproteinases 3), 15-PGDH (15-hydroxyprostaglandin dehydrogenase), or EMT (epithelial–mesenchymal transition)." (PMID 33805513, 2021).
chondrosarcoma (7 papers, 2016 to 2025). A malignant cartilaginous matrix-producing mesenchymal neoplasm arising from the bone and soft tissue. "A main target of miR-101 in Chondrosarcoma is TIMP-3 (tissue inhibitor of metalloproteinases-3), a critical regulator of metalloproteinase activity that preserves extracellular matrix integrity." (PMID 40429954, 2025). "We demonstrated that this mode of binding is able to support biologically relevant bridging of the MMP to LRP-1, as TIMP-3 was able to promote MMP-1 endocytosis by HTB94 chondrosarcoma cells." (PMID 32694578, 2020). "We previously showed that the rate of TIMP-3 endocytosis by LRP1 can be quantified by adding purified FLAG-tagged recombinant TIMP-3 (1 nM) to HTB94 chondrosarcoma cells and monitoring its disappearance from the medium." (PMID 28798097, 2017). "The ability of the analogs to promote TIMP-3 accumulation was assessed by incubating HTB94 chondrosarcoma cells with suramin or the suramin analogs (200 μg/ml) for 36 hours and quantifying TIMP-3 levels in the medium by immunoblotting." (PMID 28798097, 2017). "It has been shown that S1P could suppress tumor cell migration and downregulate MMP-2 expression in chondrosarcoma cells through upregulation of tissue inhibitor of metalloproteinase‐3 (TIMP‐3), which is the target miR-101." (PMID 35201458, 2021). "Thus, the S1P/TIMP-3/miR-101 pathway determines the metastasis of chondrosarcoma." (PMID 35201458, 2021). "We provide evidence suggesting that TIMP3, IGFBP5, and BMP2 are direct targets of Gli-mediated Hh signaling with implications for chondrosarcoma pathology, including potential cross-talk between TGF-beta signaling and Hh signaling." (PMID 30695055, 2019).
Hypertension (7 papers, 2016 to 2023). The presence of chronic increased pressure in the systemic arterial system. "Current studies found that TIMP3 gene polymorphisms were associated with carotid plaques, hypertension, and cancer." (PMID 36767251, 2023). "TIMP-3 loss caused augmented remodelling of the abdominal aorta, thereby leading to exacerbated aortic aneurysm, in the angiotensin II-induced murine model of hypertension." (PMID 35207132, 2022). "Therefore, this study explored whether TIMP3 polymorphism is associated with hypertension-related chronic kidney disease (CKD)." (PMID 36767251, 2023). "Whether TIMP3 polymorphisms are associated with hypertension-related CKD remains to be explored." (PMID 36767251, 2023). "A protective role for TIMP-3 in hypertension and myocardial vascular remodeling in vivo was demonstrated by exposing Timp3-null mice to Nω-nitro-L-arginine methyl ester (L-NAME)-induced hypertension." (PMID 35207132, 2022). "In turn, Timp3 repression allowed the costimulation of T cells and their deployment toward classical organs involved in hypertension." (PMID 33218096, 2020). "Genotypes of TIMP3 are related to hypertension and cardiovascular diseases." (PMID 36767251, 2023). "This supports a significant role for TIMP-3 in regulating hypertension." (PMID 35444693, 2022). "Hypertension, a major risk factor for cardiovascular disease, is finely regulated by ectodomain shedding (i.e., shedding of angiotensin-converting enzyme type 2 (ACE2)), ECM remodelling and inflammation, suggesting a critical role for TIMP-3 in the process." (PMID 35207132, 2022). "TIMP-3 can inhibit MMP-2, MMP-3, and MMP-9 which regulate ECM structure and vascular remodelling and consequently affect hypertension-induced stroke." (PMID 35444693, 2022).
lung fibrosis (7 papers, 2016 to 2025). "We identified over 2,500 O-GlcNAc modified proteins including α-SMA, TIMP1, TIMP3, Smad4, Smad5 and Smad3 have been implicated in pulmonary fibrosis." (PMID 38665916, 2024). "In addition, in idiopathic pulmonary fibrosis characterized by fibroblast expansion and extracellular matrix accumulation, TIMP3 gene expression is increased and the protein is localized to fibroblastic foci and extracellular matrix." (PMID 27601084, 2016). "In idiopathic pulmonary fibrosis (IPF) tissues, increased TIMP-3 expression has been observed in fibroblastic foci and ECM." (PMID 32440328, 2020). "Accordingly, it is proposed that NAC may inhibit bleomycin-induced development of pulmonary fibrosis by increasing the MMP-9/TIMP-1 and MMP-9/TIMP-3 ratios, which eventually increases the degradation of collagen in the lungs to prevent its excessive deposition in the form of fibrosis." (PMID 32440328, 2020). "Lastly, the concomitant increase in the gene transcripts of protease inhibitors, TIMP1, TIMP3, and SERPINE1, suggest that CaSR may facilitate a profibrotic environment promoting a non-degrading collagen-rich ECM, which is a defining feature of human and animal models of lung fibrosis." (PMID 40305220, 2025).
macular dystrophies (7 papers, 2020 to 2025). "Timp3 is a secreted matrix metalloprotease inhibitor that has been implicated in multiple diseases ranging from cardiomyopathies to macular dystrophies, but subcellular RNA localization patterns have not been reported." (PMID 39699003, 2024). "Sorsby Fundus Dystrophy (SFD) is an autosomal dominant, fully penetrant, macular dystrophy with early onset of symptoms, usually in the third or fourth decade of life and is caused by specific mutations in the Tissue Inhibitor of Metalloproteinase-3 (TIMP3) gene." (PMID 36430707, 2022). "SFD (TIMP3, OMIM #188826: autosomal dominant) is a macular dystrophy characterized by central vision loss during the fourth or fifth decade of life." (PMID 38610844, 2024). "We searched the electronic patient records of our large inherited retinal disease cohort, quantifying numbers of males and females with the more common (non-ABCA4) inherited macular dystrophies (associated with BEST1, EFEMP1, PROM1, PRPH2, RP1L1, and TIMP3)." (PMID 38700873, 2024).
preeclampsia (7 papers, 2018 to 2025). Preeclampsia is a hypertensive disorder of pregnancy that is characterized by new-onset hypertension with proteinuria presenting after 20 weeks of gestation, and depending on mild or severe forms may initially present with severe headache, visual disturbances, and hyperreflexia. "Moreover, two studies were conducted for TIMP1 and TIMP3 gene polymorphisms in preeclampsia and showed the association for TIMP1 rs20705558 and TIMP3 rs80272 polymorphisms." (PMID 35885543, 2022). "Additionally, this list included several genes associated with preeclampsia (PE) such as TIMP3, Wnt regulator DKK1, fibronectin FN1, cannabinoid receptor CNR1, neurokinin receptor TAC3, retinol binding protein RBP4, and prolactin PRL." (PMID 30131724, 2018). "A hypomethylation of TIMP3, an inhibitor of MMP, has also been found in preeclampsia, causing increased transcription of TIMP3, hence inhibiting angiogenesis and vascular endothelial growth factors." (PMID 34805141, 2021). "Recent studies have suggested that preeclampsia-specific DNA methylation patterns in the placenta, e.g., TIMP metallopeptidase inhibitor 3 (TIMP3) and RASSF1A promoters, can be detected in maternal circulation." (PMID 31369552, 2019). "Both proteins have an inhibitory function on trophoblast migration and invasion, and TIMP-3 is the major tissue metalloproteinase inhibitor at the maternal–fetal interface, which is up-regulated in preeclampsia." (PMID 30135684, 2018). "Recent findings indicate placental HDAC9 is diminished in preeclampsia, and a loss of HDAC9 deters placental trophoblast cell migration and invasion via hyperacetylation of the tissue inhibitor of metalloproteinases 3 (TIMP3) promoter, increasing TIMP3 levels." (PMID 41416997, 2025). "Overall, we propose that SPHKs‐dependent regulation of TIMP3 might play an essential role in preeclampsia." (PMID 34262394, 2021). "In preeclampsia, HDAC9 was downregulated, and knockdown of HDAC9 upregulated the expression of TIMP3 in HTR‐8/SVneo cells." (PMID 34262394, 2021).
aneurysm (6 papers, 2018 to 2025). Bulging or ballooning in an area of an artery secondary to arterial wall weakening. "Interestingly, TIMP3 is highly overexpressed in AAA tissue, and deficiency of TIMP3 in an aneurysm mouse model showed enhanced AAA development." (PMID 40981182, 2025).
breast tumors (6 papers, 2007 to 2024). "Nevertheless, transgenic mice deficient in TIMP3 show delayed breast tumour development, progression, and decreased incidence." (PMID 38542164, 2024). "Moreover, primary breast tumour tissue shows a significantly higher proportion of TIMP3 methylation than matched normal tissue." (PMID 38542164, 2024). "However, we also found that TIMP-3 expression by fibroblastic cells, but not by tumoural cells, correlates positively with the occurrence of distant metastases, reflecting the existence of other mechanisms in the molecular biology of the breast tumours in which this TIMP might be implicated." (PMID 17342087, 2007).
dilated cardiomyopathy (6 papers, 2011 to 2022). Cardiomyopathy which is characterized by dilation and contractile dysfunction of the left and right ventricles. "In agreement, loss of TIMP-3 function in mice triggered spontaneous left ventricular dilatation, cardiomyocyte hypertrophy and contractile dysfunction, resembling the symptoms of human dilated cardiomyopathy." (PMID 35207132, 2022). "On the other hand, TIMP-3 levels are reduced in patients with dilated cardiomyopathy, suggesting a protective role for the inhibitor." (PMID 35207132, 2022). "TIMP3 is involved in various process of cardiac remodeling and its level is reduced in ischemic and dilated cardiomyopathy." (PMID 32612540, 2020). "In the failing heart of patients with ischemic cardiomyopathy (ICM) or dilated cardiomyopathy (DCM), TIMP1 and TIMP3 levels were reduced with no change in TIMP2 and TIMP4, except TIMP4 protein decreased in ICM myocardium; however, myocardial levels of all four TIMPs were increased in another study." (PMID 32612540, 2020).
endometrial cancer (6 papers, 2000 to 2024). Primary or metastatic malignant neoplasm involving the endometrium (mucous membrane that lines the endometrial cavity). "Further studies with larger sample sizes are required to elucidate the role of TIMP3 in endometrial cancer." (PMID 38542164, 2024). "1,25-dihydroxyvitamin D, an anticancer agent, was shown to inhibit cell proliferation and invasion of endometrial cancer cells via upregulating TIMP-3." (PMID 33126605, 2020). "Such as miR-103 can post-transcriptionally down-regulate the expression of the tumor suppressor gene tissue inhibitor of metalloproteinase 3 (TIMP-3) and promote growth and invasion of endometrial cancer cell lines." (PMID 24828205, 2014). "Three genes (Decorin, TIMP3 and Cyclin D1) were identified to be differentially expressed between the benign endometrial tissue sample and the endometrial carcinoma samples (tissue and cell-lines)." (PMID 10901378, 2000). "However, the relationship between TIMP3 and endometrial cancers remains unclear." (PMID 38542164, 2024). "Current research shows that endometrial cancer expresses more TIMPs (Tissue Inhibitors of Metalloproteinases), including MMP26 (Matrix Metalloproteinase 26), TIMP-3 (Tissue Inhibitor of Metalloproteinases-3), and TIMP-4(Tissue Inhibitor of Metalloproteinases-4)." (PMID 38782818, 2024).
endometriosis (6 papers, 2010 to 2024). The growth of functional endometrial tissue in anatomic sites outside the uterine body. "In another study, it was shown that eutopic endometrium and ectopic lesions of women with endometriosis had lower levels of TIMP-3 mRNA expression, while the MMP-9 mRNA level was solely enhanced in ectopic lesions." (PMID 36235740, 2022). "MiR-181c suppression of TIMP3 expression may contribute to endometriosis by regulating cell dysfunction and angiogenesis." (PMID 35626707, 2022). "Through modulating TIMP3, miR-191 could also promote cell proliferation and invasion of endometriosis cells." (PMID 34659566, 2021). "TIMP3 is a member of the metalloproteinase family and may be a key factor regulating cell proliferation and invasion of endometriosis and EAOC cells." (PMID 34659566, 2021). "Dong found that miR-191 could directly regulate TIMP3 expression in both endometriosis and EAOC cells." (PMID 34659566, 2021). "We identified that genes involved in immune surveillance, such as TIMP3 and CXCL14 were increased in the decidualizing stromal cells from donors with endometriosis relative to cells from normal donors." (PMID 38402336, 2024). "Their findings show that both ectopic and normal endometrium of patients with endometriosis, may be more invasive and more capable of being implanted in the peritoneum because of the increased expression of MMP and decreased expression TIMP-3 in comparison with women without endometriosis." (PMID 24294950, 2013).
fibrosis (6 papers, 2020 to 2022). the formation of excess fibrous connective tissue in an organ or tissue in a reparative or reactive process. "Deficiency of TIMP3 led to extensive cardiac fibrosis through activation of TNF-α, TGFβ1 and downstream molecules Smad2/3 after pressure overload in mice, which could be inhibited by a TGFβ1 neutralizing antibody." (PMID 34778374, 2021). "Molecular analysis also showed a most significant downregulation of key profibrogenic genes α-SMA, Collagen I, and TIMP3 in fibrosis mice injected with 3D-Exo." (PMID 34930304, 2021). "The protein levels of Nrf2, HO-1, α-SMA, Collagen I, Collagen III, TIMP1 and TIMP3 were markedly increased in fibrosis mice compared with control mice." (PMID 34456904, 2021). "In addition, reduced expression of TIMP-3 that inhibits the proteolytic activity of MMPs observed in CHC patients with F3/F4 suggests a possible shift towards maintenance of the ECM structure in patients with fibrosis." (PMID 36556936, 2022). "TIMP3 is an essential mediator of kidney injury, and the lack of TIMP3 increases interstitial nephritis and fibrosis." (PMID 32309847, 2020).